NFS1 (NFS1 cysteine desulfurase)
Diseases named in the same sentence as NFS1 in open-access papers (continued):
Sharing a sentence is not in itself a finding about the gene and the disease.
infection (8 papers, 2014 to 2024). The state of being infected such as from the introduction of a foreign agent such as serum, vaccine, antigenic substance or organism. "Another NCR encoding gene, NFS1, is also expressed in the proximal infection zone and the interzone, and functions in provoking bacterial cell death and early nodule senescence." (PMID 33995430, 2021). "The Nitrogen Fixation S (NIFS)-like 1 (NFS1) and Mitochondrial Ferredoxin-1 (MFDX1) genes are part of a set of 27 Fe-S cluster genes induced after infection with host and nonhost pathogens in Arabidopsis." (PMID 34281196, 2021). "At least two mechanisms underlie this incompatibility; the succinoglycan of this strain does not appear to correctly promote infection in A17 and the isoforms of NCR peptides NFS1/NFS2 in this accession preclude symbiosis." (PMID 33329456, 2020).
NFS1 also shares sentences with these, for which no sentence is quoted: glioma (4 papers); colon cancer (3); malaria (3); Crohn disease (2); aortic aneurysm (1); cardiovascular diseases (1); colon adenocarcinoma (1); esophageal squamous cell carcinoma (1); idiopathic pulmonary arterial hypertension (1); intestinal cancer (1); Leukoencephalopathy (1); lung squamous cell carcinoma (1); Lyme borreliosis (1); memory impairment (1); periodontitis (1); small cell lung carcinoma (1).